CFAP45 (cilia and flagella associated protein 45)
Description:
Microtubule inner protein (MIP) part of the dynein-decorated doublet microtubules (DMTs) in cilia axoneme, which is required for motile cilia beating. It is an AMP-binding protein that may facilitate dynein ATPase-dependent ciliary and flagellar beating via adenine nucleotide homeostasis. May function as a donor of AMP to AK8 and hence promote ADP production.
Synonyms: CCDC19; NESG1; HTX11
Tractability: Small molecule: a structure with a bound ligand is known. Antibody: its Gene Ontology location is reachable by antibodies, with medium confidence.
Gene: Protein-coding gene on chromosome 1 (159,872,364 to 159,900,165, reverse strand). Ensembl gene ENSG00000213085.
Subcellular location: Cytoplasm, cytoskeleton, cilium axoneme; Cytoplasm, cytoskeleton, flagellum axoneme; Cell projection, cilium; Cell projection, cilium, flagellum
Subcellular location (Human Protein Atlas): End piece; Mid piece; Nucleoplasm; Principal piece; Basal body; Cytosol
Gene Ontology:
Molecular function: AMP binding; protein binding
Biological process: establishment of left/right asymmetry; flagellated sperm motility
Cellular component: 9+2 motile cilium; axonemal microtubule; axoneme; cilium; sperm end piece; sperm flagellum; sperm midpiece; sperm principal piece; axonemal B tubule inner sheath; nucleus; 9+0 motile cilium; motile cilium; polymeric cytoskeletal fiber
Genetic constraint (gnomAD): Loss-of-function variants: 41 observed, 74.63 expected, observed/expected ratio (o/e) 0.55, 90% interval 0.43 to 0.71. The upper end of that interval is the gene's LOEUF score, 0.71, which puts it in group 2 of 6, group 1 being the genes least tolerant of losing a copy. Missense variants: 685 observed, 733.88 expected, observed/expected ratio (o/e) 0.93, 90% interval 0.88 to 0.99. Synonymous variants: 223 observed, 258.7 expected, observed/expected ratio (o/e) 0.86, 90% interval 0.77 to 0.96.
Homologues: Orthologues: chimpanzee CFAP45 (99% identical), macaque CFAP45 (99% identical), dog CFAP45 (89% identical), guinea pig CFAP45 (89% identical), rabbit CFAP45 (88% identical), pig CFAP45 (86% identical), rat Cfap45 (85% identical), mouse Cfap45 (83% identical), tropical clawed frog cfap45 (59% identical), zebrafish cfap45 (47% identical), Drosophila melanogaster CG11449 (24% identical).
Diseases named in the same sentence as CFAP45 in open-access papers:
CFAP45 is named in the same sentence as 35 diseases in open-access papers, as found by Europe PMC text mining. Sharing a sentence is not in itself a finding about the gene and the disease. The quoted sentences say what the papers report.
nasopharyngeal carcinoma (7 papers, 2011 to 2022). A carcinoma arising from the nasopharyngeal epithelium. "One intergenic and one upstream gene variant in the TFBS of CFAP45 (cilia and flagella associated protein 45, also termed CCDC19 and NESG1) had higher differences in allele frequency and whose downregulation is associated with lung and nasopharyngeal carcinoma." (PMID 36011407, 2022).
bladder cancer (6 papers, 2019 to 2023). "MAGI2-AS3 could serve as a competing ceRNA for miR-15b-5p that targets CCDC19 (CFAP45, cilia, and flagella associated protein 45), a tumor suppressor in bladder cancer." (PMID 34503076, 2021).
asthenospermia (4 papers, 2020 to 2024). "Deficiency of CFAP45 in humans and mice has been reported that led to situs inversus totalis and asthenospermia." (PMID 37236356, 2023). "Here, we describe a deficiency of cilia and flagella associated protein 45 (CFAP45) in humans and mice that presents a motile ciliopathy featuring situs inversus totalis and asthenospermia." (PMID 33139725, 2020). "Deficiency of CFAP45 in humans and mice is associated with asthenozoospermia." (PMID 37236356, 2023). "CFAP45 loss-of-function mutations in humans as well as CRISPR/Cas9 ablation of Cfap45 in mice cause LRA abnormalities including situs inversus totalis as well as asthenospermia, due to dyskinetic beating of embryonic nodal cilia and sperm flagella, respectively." (PMID 33139725, 2020). "Cfap45−/− males also displayed asthenospermia; under conditions inducing hyperactivation (see “Methods”), Cfap45−/− sperm did not achieve the high amplitude and degree of flagellar bending and curvature observed in control sperm." (PMID 33139725, 2020). "Here we describe CFAP45 deficiency in man and mouse that causes a motile ciliopathy featuring LRA abnormalities (situs inversus totalis, heterotaxy) as well as asthenospermia." (PMID 33139725, 2020). "As a CFAP45-binding partner, CFAP52 may play a role similar to that of CFAP45 because Cfap52 knockout also leads to asthenozoospermia-like phenotype in mice and the expression level of CFAP45 was significantly decreased in Cfap52−/− sperm lysate." (PMID 37236356, 2023). "Recently, it has been reported that lack of CFAP45 in both humans and mice resulted in asthenozoospermia." (PMID 37236356, 2023). "Deleterious variants in two other genes, CFAP45/CCDC19/NESG1, and CFAP52/WDR16, have been found in human individuals whose clinical presentation, with situs inversus and asthenozoospermia, but only mild respiratory symptoms, did not allow for classifying them as classical PCD cases." (PMID 36901899, 2023).
ciliopathy (4 papers, 2019 to 2023). A genetic disorder of the cellular cilia or the cilia anchoring structures, the basal bodies, or of ciliary function. "Similar to CFAP45-deficient individuals, Cfap45−/− offspring exhibited a motile ciliopathy phenotype." (PMID 33139725, 2020). "Proteomic profiling links CFAP45 to an axonemal module including dynein ATPases and adenylate kinase as well as CFAP52, whose mutations cause a similar ciliopathy." (PMID 33139725, 2020). "CFAP45 and PROM1 are found in both atypical and secondary ciliopathies, whereas TTC26, SCLT1, DNAJB11, DYNC2LI1, ALMS1, IFT80 and IFT74 are shared between primary and atypical ciliopathies." (PMID 37542408, 2023).
Infertility (2 papers, 2020 to 2023). "Together, our studies demonstrate that CFAP52 plays an essential role in sperm motility by interacting with CFAP45 in sperm flagellum, providing insights into the potential pathogenesis of the infertility of the human CFAP52 mutations." (PMID 37236356, 2023).
non-small cell lung carcinoma (2 papers, 2014 to 2022). A group of at least three distinct histological types of lung cancer, including non-small cell squamous cell carcinoma, adenocarcinoma, and large cell carcinoma. "In our previous research, we cloned and revised the coding sequence of NESG1 (also known as CFAP45 and CCDC19) and subsequently confirmed that it acts as a potential tumor suppressor in NPC and non-small cell lung cancer 12-14." (PMID 35844805, 2022).
glioma (1 paper, 2021). A benign or malignant brain and spinal cord tumor that arises from glial cells (astrocytes, oligodendrocytes, ependymal cells). "In glioma grade III, highly activated DEGs included CFAP45, PLBD1, RASSF9, IGKV3-11, IGKV1-5, and NTS, while highly downregulated DEGs included NPAS4 and LINC01007." (PMID 33948562, 2021).
Hydrocephalus (1 paper, 2020). Hydrocephalus is an active distension of the ventricular system of the brain resulting from inadequate passage of CSF from its point of production within the cerebral ventricles to its point of absorption into the systemic circulation. "Hydrocephalus was observed in both male and female Cfap45−/− mice." (PMID 33139725, 2020).
Situs inversus totalis (1 paper, 2020). "Consistent with Cfap45 expression in the mouse left–right organizer (LRO) and specific CFAP45 localization to motile cilia of the LRO, Cfap45−/− offspring presented LRA abnormalities including situs inversus totalis (see also “Methods”)." (PMID 33139725, 2020).
viral infection (1 paper, 2025). "The median expression of some genes (CTBP1, LAPTM4B, CFAP45, DSC2, LAMP1, EXOG, RPS21, and SIRPB1) was higher in bacterial compared to viral infection." (PMID 41496780, 2025).
CFAP45 also shares sentences with these, for which no sentence is quoted: cancer (9 papers); tumor (9); lung carcinoma (3); asthma (2); breast carcinoma (2); lymph node metastasis (2); adenocarcinoma (1); bronchiectasis (1); chronic lymphocytic leukemia (1); gastric cancer (1); Intellectual disability (1); lung adenocarcinoma (1); mantle cell lymphoma (1); metastasis (1); Neurodevelopmental delay (1); pancreatic cancer (1); papillary thyroid carcinoma (1); post-traumatic stress disorder (1); prostate carcinoma (1); renal carcinoma (1); respiratory diseases (1); situs inversus (1); squamous cell carcinoma (1); squamous cell lung carcinoma (1); synucleinopathy (1).